CACNA1A (calcium voltage-gated channel subunit alpha1 A)
Diseases named in the same sentence as CACNA1A in open-access papers (continued):
Sharing a sentence is not in itself a finding about the gene and the disease.
hereditary ataxia (11 papers, 2016 to 2026). An instance of an atactic disorder that is caused by an inherited genomic modification in an individual. "In patients with suspected hereditary ataxia, we identified expansions in loci that had not been assessed as part of routine diagnostic workup within the NHS at the time of recruitment, including ATN1, ATXN2, ATXN3, ATXN7, CACNA1A, FXN, TBP, and HTT." (PMID 35182509, 2022).
Tremor (10 papers, 2013 to 2025). An unintentional, oscillating to-and-fro muscle movement about a joint axis. "Paroxysmal head tremor has been reported with CACNA1A mutation but in conjunction with persistent cerebellar features as opposed to PNKD." (PMID 24171125, 2013). "Progressive tremor was associated with genes CACNA1A, CSTB, and SAMD9L." (PMID 40326640, 2025). "Furthermore, tremor is a prevalent movement disorder in CACNA1A mutation-related DEE patients, occurring in approximately 55.2% of cases." (PMID 40217411, 2025). "Static tremors have been reported in patients with EIEE caused by CACNA1A variants." (PMID 33425808, 2020).
type 2 diabetes (9 papers, 2016 to 2025). "Among URGTG, three genes, AKT1S1, TNFRSF1B, and CACNA1A, were found to be associated with obesity-related pathways (in KEGG database), which were thermogenesis (hsa04714), the adipocytokine signaling pathway (hsa04920), and type II diabetes mellitus (hsa04930), respectively." (PMID 36499541, 2022). "Pathway analysis for CACNA1A and PRDM16, the two genes suggestively associated with tea consumption, showed enrichment for white Adipose tissue browning (P = 3.2 × 10−5), nNOS signalling in skeletal muscle cells (P = 3.6 × 10−3) and Maturity onset diabetes of young (MODY) (P = 5.2 × 10−3)." (PMID 33990564, 2021). "CACNA1A is a Calcium Channel, Voltage-Dependent, P/Q Type, Alpha 1A Subunit; SLC2A2 is a solute carrier family 2 (Facilitated Glucose Transporter); hsa04930 is pathway related to type 2 diabetes." (PMID 27984588, 2016). "The impact analysis also revealed the enrichment of the “Type II diabetes mellitus” pathway resulting from the upregulation of MAPK10 and IRS2 and the downregulation of CACNA1A and SOCS2, a signature that may upregulate the insulin receptor (INSR), PI3K, and insulin resistance." (PMID 36835058, 2023).
generalized epilepsy (7 papers, 2015 to 2024). Epilepsy that is characterized by generalized seizure types and may have typical interictal and/or ictal EEG findings that accompany generalized seizure types (for example generalized spike-wave). "A de novo heterozygous nonsense mutation in CACNA1A gene encoding the CaV2.1 channel has been reported in a young male patient affected with generalized epilepsy." (PMID 25893123, 2015). "Also, axonal sprouting of SOM-INs and gain of dendritic inhibition associated with loss of parvalbumin synaptic inhibition in the CACNA1A mouse model of generalized epilepsy is reversed by rapamycin treatment and thus mTORC1-dependent." (PMID 37400913, 2023). "Although data on specific gene in idiopathic generalized epilepsy is relatively scarce, mutations of voltage gated sodium channel subunit genes (CACNB4) and nonsense mutations in voltage gated calcium channels (CACNA1A) have been linked to idiopathic generalized epilepsy in two families." (PMID 25893123, 2015).
ischemic stroke (7 papers, 2016 to 2020). A stroke disorder caused by obstruction of blood flow to the brain, due to thrombotic (local blood clot formation) or embolic (due to a blood clot or other material traveling from another site) event. "Our report presents the second described case of recurrent ischemic strokes in a patient with CACNA1A mutation and expands the phenotypic heterogeneity related to variants in this gene." (PMID 32692472, 2020). "To date, ischemic stroke caused by a CACNA1A variant has only been reported once in the literature." (PMID 32692472, 2020). "We present the second case of recurrent ischemic strokes in a patient with CACNA1A mutation." (PMID 32692472, 2020).
schizophrenia (7 papers, 2016 to 2025). A major psychotic disorder characterized by abnormalities in the perception or expression of reality. "For example, HTT, ATXN1, ATXN7, and CACNA1A were associated with neuropsychiatric disorders such as depression and schizophrenia." (PMID 41254939, 2025). "Among the top candidate genes pinpointed by the analysis of the link between neuronal RG differentiation and schizophrenia are ZDHHC8, NCOR2 and CACNA1A, which were previously implicated as SCZ risk genes." (PMID 34194671, 2021).
Vertigo (7 papers, 2014 to 2026). An abnormal sensation of spinning while the body is actually stationary. "Transitory vascular disturbances in cerebellar cortex, where CACNA1A is abundantly expressed, were demonstrated in temporal cortex and the vestibular nuclei respectively during episodes of torticollis and vertigo." (PMID 25928129, 2014). "Mutations in the CACNA1A and PRRT2 genes, which are associated with FHM, have been found in some patients with benign paroxysmal torticollis and benign paroxysmal vertigo, thus confirming their link to migraine." (PMID 25928129, 2014). "Benign paroxysmal torticollis (BPT), benign paroxysmal vertigo (BPV), and benign paroxysmal tonic upgaze (BTU) may be associated with CACNA1A variants." (PMID 40111503, 2025).
absence seizures (6 papers, 2020 to 2026). "Cacna1a missense mutation mouse model of absence seizures revealed that the cerebellar neurons are powerful regulators of the pathological oscillations in the thalamocortical system." (PMID 37555011, 2023). "CACNA1A variants and absence seizures are related to each other, and this issue has been shown in rodents and humans." (PMID 34727962, 2021). "In contrast to the ameliorating effect of Cacna1g on the mouse model of Dravet syndrome, CACNA1A has a worsening effect on Dravet syndrome, meaning subjects carrying both SCN1A and CACNA1A variants develop absence seizures earlier and more frequently than patients with only SCN1A mutations." (PMID 39513870, 2024). "In addition, the role of CACNA1A variants in developing absence seizures in dravet syndrome has been reported." (PMID 34727962, 2021). "Thus, in this study, we aimed for the first time to assess whether larval zebrafish may suffer from cacna1a-mediated absence seizures." (PMID 31875924, 2020). "On the other hand, phenytoin, another sodium channel blocker, did not affect seizure incidence in Cacna1a models of absence seizures." (PMID 31875924, 2020).
Anxiety (6 papers, 2015 to 2023). Intense feelings of nervousness, tension, or panic often arise in response to interpersonal stresses. "Next, we characterized our ePet-Cre/Cacna1a−/− and control Cacna1a+/+ mice for alterations in anxiety-like and male aggressive behavior." (PMID 35853721, 2022). "Moreover, forebrain specific CACNA1A knock-out mice showed impaired synaptic transmission at hippocampal glutamatergic synapses, deficits in spatial learning, reduced recognition memory, and reduced anxiety-like behaviors." (PMID 26566276, 2015).
spinobulbar muscular atrophy (6 papers, 2009 to 2022). "The CACNA1A calcium channel subunit in SCA6 is primarily expressed in affected cerebellar Purkinje cells, while the AR in Kennedy’s disease is principally expressed in vulnerable motor neurons." (PMID 26331033, 2014).
Encephalopathy (5 papers, 2019 to 2023). Encephalopathy is a term that means brain disease, damage, or malfunction. "Some reports indicated that a prompt recovery had been described in three patients with CACNA1A mutations through the combined use of steroids and hypertonic solutions in the course of encephalopathy and cerebral edema." (PMID 37576133, 2023). "After corticosteroids treatment, the severity and duration of acute attacks in the presence of encephalopathy and cerebral oedema in patients with CACNA1A variants were rapidly reduced." (PMID 33425808, 2020). "In the literature, a missense mutation in CACNA1A was observed in a patient affected by encephalopathy with a thin corpus callosum." (PMID 31578829, 2020).
Hypertension (5 papers, 2018 to 2025). The presence of chronic increased pressure in the systemic arterial system. "A genome-wide association meta-analysis of systolic BP, diastolic BP, and hypertension (N = 86,588 individuals) showed that genetic polymorphisms of CACNA1A were potentially associated with changes in BP and hypertension." (PMID 38542788, 2024).
paroxysmal dystonia (5 papers, 2020 to 2025). "This provides further evidence in support of our patient's novel CACNA1A mutation being the cause of her paroxysmal dystonia." (PMID 34395002, 2021). "Very recently, a multicentric study on 47 infants with CACNA1A variants revealed a high frequency of paroxysmal dystonia, especially of PTU (found in 47% of cases, while torticollis was evident in 19%)." (PMID 33737904, 2021). "Similarly, a clinical picture with early onset paroxysmal dystonia, such as BPTI, plus cerebellar signs supports the application of CACNA1A sequencing, even in the presence of a negative family history." (PMID 33737904, 2021).
status epilepticus (5 papers, 2019 to 2025). Status epilepticus is defined as a continuous seizure lasting more than 30 min, or two or more seizures without full recovery of consciousness between any of them. "In addition, CACNA1A-related epilepsy (OMIM: 617106) with multiple seizures types and status epilepticus have been described." (PMID 40703772, 2025).
diabetes (4 papers, 2017 to 2024). "The CAMK1D (OMIM 607957) gene on 10p13 and CACNA1A (OMIM 601011) on 19p13.13 are also associated with diabetes." (PMID 30212560, 2018).
lung carcinoma (4 papers, 2010 to 2022). "The SNP rs16018, a member of the family of voltage-gated calcium channels, is located in the gene CACNA1A which is upregulated in numerous types of cancer including lung cancer." (PMID 35658861, 2022). "For example, clinical studies have demonstrated overexpression of CACNA1D (Cav1.3) (L type), CACNA1A (Cav2.1) (P/Q type), and CACNA1G (Cav3.1) (T type) in lung cancer, and overexpression of CACNA1A (Cav2.1) was associated with poor prognosis." (PMID 28127114, 2017). "MS-MLPA allowed identification of a number of new and possibly interesting epigenetic alterations such as HLTF, ID4, BNIP3, H2AFX, CACNA1G, CACNA1A and TGIF genes, serving to gain more insight into the development of lung carcinomas." (PMID 20849603, 2010). "Importantly, our study identified seven novel methylated candidates in lung cancer, including HLTF, ID4, BNIP3, H2AFX, CACNA1G, CACNA1A and TGIF." (PMID 20849603, 2010).
migraine headaches (4 papers, 2014 to 2024). "The discovery of novel genetic variants of the CACNA1A gene associated with familial hemiplegic migraine type I (FHM1) has sparked further investigation into the variants of genes within the CACNA family among individuals suffering from headaches." (PMID 38785745, 2024).
neuropathy (4 papers, 2010 to 2026). A disorder affecting the nervous system that manifests with pain, tingling, numbness, and/or muscle weakness. "As variants in CACNA1A can also cause an FMH phenotype in addition to an inherited neuropathy, segregation of the CACNA1A c.6692G > A variant was conducted." (PMID 31852952, 2019). "The allelic heterogeneity in the MPZ gene is characterized by different types of neuropathy, in contrast to different disorders caused by mutations in the CACNA1A gene." (PMID 20385006, 2010).
sporadic hemiplegic migraine (4 papers, 2012 to 2022). A migraine disorder characterized by an aura that includes motor weakness and the absence of family history. "Sporadic hemiplegic migraine (SHM) is another rare disease involving CACNA1A variants, which seldom coexists with EA2." (PMID 35677330, 2022). "The heterogeneous spectrum of CACNA1A gene mutations probably causes sporadic hemiplegic migraine (SHM) to be misdiagnosed." (PMID 22527033, 2012).
Arrhythmia (3 papers, 2022). Any cardiac rhythm other than the normal sinus rhythm. "Additionally, while the CACNA1A gene was expressed in cardiac tissue, it was not determined whether the variant influenced arrhythmia through neurons or the function of cardiomyocytes." (PMID 35154276, 2022).
epileptic syndromes (3 papers, 2024 to 2025). "In one study, specific gene sequencing identified CACNA1A as one of the pathogenic mutant genes present in epileptic syndromes." (PMID 39161505, 2024). "Variants in CHD2, CACNA1A, SCN2A, SCN9A, and other genes identified in our cohort have been previously linked to epileptic syndromes." (PMID 41302954, 2025).
eye movement disorders (3 papers, 2016 to 2022). "A second study retrospectively analyzed eye movement disorders in children with CACNA1A mutations, most frequently describing paroxysmal tonic upgaze, saccade dysmetria, and strabismus." (PMID 36353133, 2022). "Furthermore, a study on nine children with SCA6 also concluded that eye movement disorders, such as paroxysmal tonic upgaze and dysmetric saccades, could be considered the early manifestations of CACNA1A mutations in children." (PMID 35326260, 2022).
Obesity (3 papers, 2021 to 2024). Accumulation of substantial excess body fat. "Among all common DEGs, three genes (TNFRSF1B, CACNA1A, and AKT1S1) were found to be associated with obesity-related pathways from the Kyoto Encyclopedia of Genes and Genomes (KEGG) pathway database." (PMID 36499541, 2022).
cerebral oedema (2 papers, 2020). "Genetic variation in the CACNA1A gene is associated with cerebral palsy." (PMID 32850550, 2020).
Hemiconvulsion-hemiplegia-epilepsy syndrome (2 papers, 2020 to 2025). "Hemiconvulsion-hemiplegia-epilepsy syndrome is also associated with CACNA1A variants." (PMID 40111503, 2025).
leukemia (2 papers, 2015 to 2024). A malignant (clonal) hematologic disorder, involving hematopoietic stem cells and characterized by the presence of primitive or atypical myeloid or lymphoid cells in the bone marrow and the blood. "In the present study, we found that CACNA1A was highly expressed in most cancers, including leukemia and ovarian cancer." (PMID 26147197, 2015). "Overall, our bioinformatics analysis indicated that CACNA1A may be a potential therapeutic target for leukemia, lung, ovarian, brain, uterine, and cervical cancers." (PMID 26147197, 2015). "Leukemias such as chronic lymphocytic leukemia, monoclonal gammopathy of undetermined significance, skin squamous cell carcinoma, and marginal zone b-cell lymphoma all presented significant overexpression of CACNA1A relative to control samples." (PMID 26147197, 2015). "Thus, we speculated that leukemia patients with high expression of CACNA1S, CACNA1C, or CACNA1A relative to normal samples are likely to experience metastasis of the cancer cells to the lungs, heart, central nervous system, and other tissues." (PMID 26147197, 2015).
ovarian carcinoma (2 papers, 2012 to 2015). A malignant neoplasm originating from the surface ovarian epithelium. "When applying Kaplan-Meier plotter analysis, correlations between the overexpression of CACNA1A and overall lower survival rates in lung cancer and ovarian cancer were shown by using the GSE9891 database." (PMID 26147197, 2015). "The high expression of CACNA1A shows that this gene is possibly involved in the onset and progression of lung and ovarian cancer (poor prognosis)." (PMID 26147197, 2015). "The methylation frequencies of RASSFIA, CDH13, CACNA1A, HIN-1, DKN2B, sFRP5, ID4, and ESR were significantly higher in the clear-cell type of ovarian carcinoma than in the non-clear-cell type." (PMID 22871047, 2012). "Our study identified eight candidate genes with promoter methylation in OCCA including CACNA1A and HIN-1, which were significantly higher than those of the non-clear-cell type of ovarian carcinoma." (PMID 22871047, 2012). "Moreover, the methylation frequencies of RASSFIA, CDH13, CACNA1A, HIN-1, DKN2B, sFRP5, ID4, and ESR were significantly higher among OCCA than those in non-clear-cell types of ovarian carcinoma." (PMID 22871047, 2012).
prostate carcinoma (2 papers, 2015 to 2017). A carcinoma that arises from epithelial cells of the prostate gland. "In RPE cells, we suppose that cAMP leads to the activation of protein kinase A, which in turn opens L-type Ca2+ (e.g., CACNA1A: 3.85 mFPKM; CACNA1A: 2.63 mFPKM) or TRP channels (e.g., TRPM3: 1.71 mFPKM; TRPM4: 7.76 mFPKM), as shown in epidermal melanocytes and prostate cancer cells." (PMID 29249973, 2017).
albinism (1 paper, 2020). A congenital disorder characterized by partial or complete absence of melanin pigment in the eyes, hair, or skin. "The genes identified for MAC were KMT2D, MAB2IL2, ALDH1A3; ASDA were KERA, PAX6, MYOC, TGFBI, and SLC4A11; congenital cataract were CRYBB2, EPHA2, HSF4 and BCOR; infantile nystagmus were CACNA1A and FRMD7; and albinism were OCA2, GPR143, HPS6 and SLC38A8." (PMID 32830442, 2020).
angina (1 paper, 2023). "Similarly, evidence for T2D risk reduction was also observed for angina risk reduction via verapamil as proxied by reduced CACNA1A expression (T2D OR = 0.17, 95% CI = 0.10, 0.29, p = 2.1 x 10−10 [IVW MR association])." (PMID 37399599, 2023).
ataxic disorders (1 paper, 2022). "Consistent with previous studies in ataxic disorders, CACNA1A patients displayed lower average gait speed, shorter steps and increased stride length variability at IGA." (PMID 34755206, 2022). "Contrasting with the typical gait pattern of ataxic disorders, CACNA1A patients did not display a longer stand phase nor a widened gait base." (PMID 34755206, 2022).
attention deficit hyperactive disorder (1 paper, 2021). "Furthermore, our review has revealed CACNA1A, CACNA1C and CACNA2D1 as the candidate genes for attention deficit hyperactive disorder." (PMID 33985586, 2021).
autosomal recessive spastic ataxia (1 paper, 2021). Autosomal recessive form of spastic ataxia. "Three patients had autosomal recessive spastic ataxia of Charlevoix-Saguenay (ARSACS) and three patients had point mutations in CACNA1A." (PMID 34600502, 2021).
blepharospasm (1 paper, 2019). "Interestingly, a recent study showed that deleterious variants in CACNA1A, REEP4, TOR2A, ATP2A3, HS1BP3, GNA14, and DNAH17 were involved in blepharospasm, and none of these variants except for CACNA1A has been reported to be associated with blepharospasm." (PMID 32038460, 2019).
cardiac arrest (1 paper, 2025). Cessation of breathing and/or cardiac function. "The CACNA1A missense variant p.Ser218Leu is associated with a gain of channel function and in the homozygous CACNA1A218 mouse, in contrast to the wildtype, seizures led to SUDEP triggered by brainstem spreading depolarization with subsequent apnea and cardiac arrest." (PMID 40703772, 2025).
Cerebellar hypoplasia (1 paper, 2023). Cerebellar hypoplasia is a descriptive term implying a cerebellum with a reduced volume, but a normal shape and is stable over time. "Seven probands carry causative variants in well-known genes associated with CA or cerebellar hypoplasia: SETX, CACNA1G, CACNA1A, CLN6, CPLANE1, and TBCD." (PMID 38003592, 2023).
cervical dystonia (1 paper, 2021). "The report of another patient with cervical dystonia and a mutation in CACNA1A supports the idea that our patient's cervical dystonia is due to her mutation in CACNA1A." (PMID 34395002, 2021).
Cluster headache (1 paper, 2025). A type of headache characterized by repeated attacks of unilateral pain lasting 15 to 180 minutes and associated with local autonomic signs. "Additionally, a haplotype and mutation analysis of the CACNA1A gene was conducted in a family with three cluster headache-affected members, but no mutations were identified." (PMID 39560176, 2025).